EGFR (epidermal growth factor receptor)
Diseases named in the same sentence as EGFR in open-access papers (continued):
Sharing a sentence is not in itself a finding about the gene and the disease.
glioblastoma (continued). "For instance, EGFR wild type or EGFRvIII EVs can be isolated and quantified from glioblastoma patient plasma." (PMID 36133088, 2021). "LncRNA-NEAT1 has been revealed to be modulated by the epidermal growth factor receptor (EGFR) pathway, leading to glioblastoma multiform progression by the WNT/β-Catenin Pathway by Scaffolding enhancer of zeste homolog 2 (EZH2)." (PMID 33750353, 2021). "miR-221 was up-regulated in our resistant cell lines, and this up-regulation led to a significant reduction in EGFR expression in both our cultured cell lines and a large cohort of glioblastoma patient tumor tissue." (PMID 33082482, 2020). "The most recent cIMPACT update on IDH-WT infiltrating gliomas recommends upgrading of infiltrating gliomas bearing EGFR amplification and/or 7 gain/10 loss and/or TERT mutation as glioblastoma equivalents." (PMID 33059718, 2020). "The epidermal growth factor receptor (EGFR, HER1) is a major regulator of proliferation in tumor cells and a well-known target in glioblastoma treatment." (PMID 31952211, 2020). "They propose that glioblastomas are resistant to EGFR tyrosine kinase inhibitors (TKI) because of this circuit further autonomy." (PMID 32774372, 2020). "EGFR-vIII, a constitutively active deletion mutant of EGFR that constitutes a large portion of EGFR mutants, is a therapeutic target because of its strong role in enhancing tumorigenesis and malignant progression of glioblastoma." (PMID 32051553, 2020). "Although EGFR signaling is dysregulated in other types of malignancies, including pancreatic cancer and glioblastoma, EGFR-TKI exhibits limited efficacy against these malignancies." (PMID 32764319, 2020). "Increased levels of EGFR expression are frequently involved in deregulated cell proliferation in different types of tumors, including glioblastoma, therefore we evaluated the levels of this protein by immunoblot analysis upon GOLPH3 knockdown." (PMID 33238647, 2020). "For instance, glioblastoma cells residing in hypoxic regions of a tumor overexpress EGFR (epidermal growth factor receptor), while vascular regions were enriched in platelet-derived growth factor receptor α." (PMID 33322354, 2020). "The results of the INTELLANCE 2/EORTC 1410 phase II study of Depatux-M alone and with temozolomide versus temozolomide or lomustine in progressive EGFR-amplified glioblastoma have been recently published." (PMID 32705082, 2020). "We observed several recurrent chromosomal aberrations that are often dysregulated in glioblastoma progression in both cohorts including amplification of chromosome 7 and 4, harboring EGFR and PDGFRA respectively." (PMID 32794373, 2020). "The EGFR gene is amplified in roughly 40% of glioblastomas and patients with EGFR amplified tumors frequently have a deletion mutation called EGFRvIII." (PMID 32117316, 2020). "They showed that experimentally interfering with local EGFR enhancers in EGFR-amplified glioblastoma impaired oncogene expression and cell viability in EGFR-amplified as well as non-amplified cases." (PMID 33199677, 2020). "This review focuses on both the history and future of targeting EGFR in glioblastoma, with a special emphasis on tyrosine kinase inhibitors that have already achieved success in EGFR mutant NSCLC." (PMID 33187135, 2020). "Intriguingly, Trametinib appeared to specifically reduce ZNF263 protein levels without altering those of KAP1, SUV39H2, EED, or SETDB1, implying that the activation of EGFR/MAPK led to SIX3 silencing in glioblastoma mainly through the regulation of ZNF263." (PMID 32051553, 2020). "To further confirm the relationship of EGFR-ZNF263 signaling components, we investigated the reverse phase protein array data from TCGA which contains the expression data of EGFR, EGFR-pY1068, EGFR_pY1173, and EGFR_pY992 in part of glioblastoma samples." (PMID 32051553, 2020).
glioblastoma (continued). "In the case of glioblastomas, targeted EGFR therapies have demonstrated much promise but relatively little success." (PMID 33228060, 2020). "In glioblastoma, the EGFR gene is amplified in 40% of cases, and more than 50% of cases include deletion or mutation of exon 2-7." (PMID 31979318, 2020). "Overall, our novel results establish miR-221 as a key onco-mir driving both therapy resistance and resistance-initiated glioblastoma recurrence through the regulation of EGFR expression." (PMID 33082482, 2020). "Firstly, in glioblastoma (GBM) it targets EGFR expression, making this miRNA a novel biomarker for the early diagnosis of GBM." (PMID 32605009, 2020). "We have previously shown that EGFR inhibition protects human glioblastoma cells from oxygen and nutrient deprivation." (PMID 33092032, 2020). "The results of dual luciferase reporter assays indicated that EGFR directly bind to miR-7-5p, which was also in agreement with the previous reports concerning EGFR in glioblastoma and other diseases." (PMID 32962742, 2020). "Among the 19 EGFR-amplified glioblastomas, EGFRvIII was identified in 8 patients by dPCR EGFR2/EGFR3 assay, and all were confirmed using LD-RT-PCR." (PMID 32303258, 2020). "Recent reports have shown that lipid metabolism is critical to glioma cells in terms of energy synthesis 28, 29, and fatty acids were shown to regulate the EGFR signaling pathway and to promote survival and proliferation of glioblastoma stem cells." (PMID 32328180, 2020). "Toward this end, we load irinotecan (CPT-11) to cetuximab (CET)-conjugated GO (GO-CET/CPT11) for pH-responsive drug release after endocytosis by epidermal growth factor receptor (EGFR) over-expressed U87 human glioblastoma cells." (PMID 32993166, 2020). "A quite common activating EGFR mutation consists of exons 2–7 deletion leading to a truncated EGFR variant III (EGFRvIII), which is often described in glioblastoma." (PMID 31968687, 2020). "By contrast, the IDH-WT subclass (c5) showed association with poor survival, enriched for mutations in EGFR and PTEN gene and concurrent chromosome 7 gain and 10 loss, resembling glioblastomas." (PMID 33272320, 2020). "In contrast, ZNF263 knockdown, Trametinib treatment, or ectopic expression of SIX3 prevented the tumor-promoting effects of EGFR-vIII on glioblastoma cells." (PMID 32051553, 2020). "Dual-targeting CAR-T cells against EGFR/EGFRvIII showed specific toxicity to glioblastoma in a study." (PMID 33511267, 2020). "For example, MUC4 has been shown to be involved in cell proliferation and invasion by upregulation of EGFR in glioblastoma cells." (PMID 32604718, 2020). "In summary, the EGFR/NEAT1/EZH2/β-catenin axis plays a crucial role in the development of glioblastoma." (PMID 32283739, 2020). "The EGFR signaling is activated in 60% of glioblastoma tumors and so, being a ‘critical molecule’ for glioblastoma." (PMID 33369441, 2020). "Both parental and #41R cells were exposed to 1 μM of erlotinib, gefitinib, afatinib and lapatinib for 72 h, four FDA approved agents that can inhibit EGFR and have been tested in glioblastoma clinical trials." (PMID 33082482, 2020). "Of note, the INTELLANCE 1 phase III trial using Depatux-M in EGFR-amplified newly diagnosed glioblastoma was discontinued for futility (NCT02573324)." (PMID 32705082, 2020). "EGFR-vIII ectopic expression substantially enhanced invasion and anchorage-independent growth of glioblastoma cells." (PMID 32051553, 2020). "Nevertheless, clinical cases of response to single agent cetuximab responses in EGFR-expressing recurrent glioblastoma have been reported." (PMID 33187135, 2020).
glioblastoma (continued). "Recent studies using integrated epigenome and transcriptome analyses revealed the critical role of EGFR in remodeling the epigenetic landscape of glioblastoma." (PMID 32051553, 2020). "This is quite relevant to the field of EGFR research, as both EGFR and its glioblastoma mutant EGFRvIII can be found on Flotillin1+ sEVs extracted from the blood of glioblastoma and ovarian cancer patients, as well as on CD9+/CD81+ sEVs." (PMID 33302515, 2020). "Amplification and overexpression of EGFR are a particularly striking feature of glioblastoma (GBM), observed in approximately 40% of tumors." (PMID 33081688, 2020). "Here, we evaluated the effect of miRNA-7 on EGFR expression and sensitivity of the U373-MG glioblastoma to erlotinib." (PMID 32592373, 2020). "This group detected fibrillary acid protein-positive (GFAP), CD45-negative CTCs in 20.6% of patients with glioblastoma and found to harbor specific aberrations of the primary tumor, including EGFR gene amplification, or chromosome insertions or deletions." (PMID 33053907, 2020). "To determine the expression of miR-221 and EGFR in patients, we assessed the expression of miR-221 and EGFR in a cohort of 105 primary glioblastoma patient samples." (PMID 33082482, 2020). "Further studies in glioblastoma are ongoing using EGFR, another well-known cell surface protein overexpressed in 40–60% of glioblastoma tumors." (PMID 32751977, 2020). "Deregulation of the EGFR signaling pathway activity has been shown to can be effective in resistance to EGFR-TKIs, such as Tarceva (erlotinib), in glioblastoma cells." (PMID 32592373, 2020). "Erlotinib (Tarceva), a small-molecule inhibitor that acts on the EGFR, is used as a second line treatment for glioblastoma therapy." (PMID 32592373, 2020). "Attempts to target EGFR in glioblastoma have had minimal success, especially in comparison to other tumors such as non-small cell lung cancer (NSCLC)." (PMID 33187135, 2020). "EGFR is a member of the RTKs which is over-expressed or hyperactivated in different types of human malignancies including glioblastoma." (PMID 32592373, 2020). "The experience of EGFR targeting in glioblastoma is presented in detail below, and their mechanisms of action are summarized." (PMID 33187135, 2020). "EGFR amplification and EGFR variant III (EGFRvIII), which is characterized by the deletion of exons 2–7, are the two most frequent EGFR alterations in glioblastoma observed in 40–50% and 10% of patients, respectively." (PMID 32303258, 2020). "We expressed EGFR-vIII in glioblastoma cells, which expectedly increased ZNF263 levels and decreased SIX3 levels." (PMID 32051553, 2020). "Glioblastoma is another cancer where EGFR signalling plays a pivotal role in tumorigenesis, via overexpression and the expression of truncation mutants." (PMID 33228060, 2020). "Preclinical studies using NK-92 cells transduced to express a CAR specific for EGFR have shown efficacy in tumor models of breast cancer brain metastasis, glioblastoma models and patient derived glioblastoma stem cells." (PMID 32751977, 2020). "Our data also presents some evidence for the use of a high miR-221 and low EGFR expression signature as a potential biomarker for poorer survival at recurrence in glioblastoma." (PMID 33082482, 2020). "Five EGFR-amplified glioblastomas had a lower estimated copy number by EGFR2 than those by EGFR1/EGFR3 assays; in one patient (patient #07), an EGFR2 copy number was estimated as 3.3, which was below the established cutoff." (PMID 32303258, 2020). "Overexpression of the epidermal growth factor receptor (EGFR) is observed in many tumor types including glioblastoma." (PMID 33082482, 2020). "In the present study, we applied miRNA-7 to knockdown EGFR in the U373-MG glioblastoma cells, and evaluated the role of miRNA-7 in response of glioblastoma cells to erlotinib." (PMID 32592373, 2020).
glioblastoma (continued). "miR-21 inhibitor loaded dendrimers enhance chemosensitivity of glioblastoma cells to paclitaxel through EGFR/STAT3 signaling." (PMID 33007959, 2020). "EGFR is one of the most frequently amplified genes in glioblastoma, the most frequent and lethal type of brain tumor." (PMID 33287875, 2020). "In our previous work, we found that EGFR-CAR NK cells targeted glioblastoma with both wild-type EGFR and EGFRvIII." (PMID 33287875, 2020). "In the Glioblastomas Cancer Stem Cells (GSCs), Notch and Epidermal Growth Factor receptor (EGFR) pathways are among the most frequent components involved in cell proliferation and survival." (PMID 32182759, 2020). "PIK3CA mutations and combined EGFR, PTEN, and CDKN2A alterations conferred worse prognosis in some IDH-wildtype glioblastoma subsets." (PMID 32640746, 2020). "LRIG2 promotes proliferation and inhibits apoptosis of glioblastoma cells through activation of EGFR and PI3K/Akt pathway." (PMID 32488114, 2020). "In the present work, we report a distinct mechanism by which the overexpression of the oncoprotein GOLPH3 regulates EGFR in T98G cells of glioblastoma multiforme." (PMID 33238647, 2020). "Amongst these, IDH, PDGFR, and PIK3CA alterations characterize proneural glioblastoma, EGFR amplification occurs in classical glioblastoma, and NF1, PTEN, and NFκB mutations predominate in mesenchymal subtypes." (PMID 33396284, 2020). "The failure of EGFR-directed treatments and other targeted therapies has been ascribed to the high intra-tumoral heterogeneity of glioblastoma, but other obstacles likely play a role as well." (PMID 33187135, 2020). "We also confirmed the high number of EGFR copy number amplicons in glioblastoma, including 13% of tumors (n = 8) with greater than 50 copy gains." (PMID 32303258, 2020). "We demonstrate that sub-populations of TMZ and irradiation resistant glioblastoma cells display reduced EGFR expression compared to their sensitive counterparts." (PMID 33082482, 2020). "From January 2017 to September 2019, about six major clinical trials were published, while currently there are about 19 ongoing clinical trials based on EGFR-targeting therapeutic agents and tyrosine kinase inhibition for glioblastomas." (PMID 32290213, 2020). "In genomic analysis, the presence of abnormalities in the epidermal growth factor receptor (EGFR) expression of glioblastoma is an important characteristic with clinically relevant subtypes." (PMID 32823915, 2020). "We treated glioblastoma cells with erlotinib, a selective inhibitor of EGFR, which significantly increased SIX3 expression." (PMID 32051553, 2020). "Suppression on STAT3 phosphorylation and EGFR/Akt/cyclin D1 signaling was reported to jointly contribute to cell cycle arrest in glioblastoma cells." (PMID 32877289, 2020). "The EGFR is a driver behind some solid tumours including lung, breast and glioblastoma and serves as a highly attractive target for bio-engineering EVs with EGFR targeting abilities." (PMID 33143170, 2020). "It has been well documented that the gain of chromosome 7 where EGFR located is the first event in human glioblastoma development." (PMID 32051553, 2020). "The ligand-independent EGFR oligomer, which dominates at high EGFR concentrations (relevant in EGFR overexpressed glioblastoma), is likely to have epitopes distinct from those of classic ligand-dependent dimers." (PMID 33187135, 2020). "Syntenin-1, a syndecan-binding protein, in fact appears to be co-expressed with EGFR and to regulate its signalling in both glioblastoma and urothelial cell carcinoma." (PMID 33302515, 2020). "Hyperglycemia has an adverse prognostic impact in patients affected by glioblastoma and high intracellular glucose increases resistance of glioblastoma cells to therapies targeting epidermal growth factor receptor, phosphoinositide 3-kinase and AKT." (PMID 32443613, 2020).
glioblastoma (continued). "In glioblastoma, the epidermal growth factor receptor (EGFR) antagonist nimotuzumab targeting CD133 has been shown to radiosensitize subpopulations of cells." (PMID 32158431, 2020). "In summary, high EGFR, EGFRvIII+ and BRAFV600E mutated glioblastoma and/or childhood tumors present a dependency on autophagy signaling." (PMID 32878084, 2020). "EGFR signaling plays an important role in promoting glioblastoma survival and progression and thus by targeting EGFR pathway, the cancer cells either will undergo apoptosis or becomes sensitized to chemotherapy." (PMID 32164385, 2020). "In the specific situation of EGFR amplification detection in glioblastoma sample, the ideal comparison tissue should have been healthy brain tissue, which is virtually impossible to obtain in daily practice." (PMID 32303258, 2020). "Using FISH, seven out of the 8 EGFR-amplified glioblastomas contained at least 90% cell nuclei with EGFR amplification." (PMID 32303258, 2020). "For example, most glioblastoma lines lack epidermal growth factor receptor (EGFR) amplification, while 40% of the primary tumor specimens contain this mutation." (PMID 33390879, 2020). "The randomized phase II study (INTELLANCE-2) studied Depatux-M in 260 patients with centrally-confirmed EGFR-amplified recurrent glioblastoma." (PMID 33187135, 2020). "miR‐373 targets the epidermal growth factor receptor and is a tumor suppressor in glioblastoma cells." (PMID 32118353, 2020). "The EGFR pathway is frequently mutated in glioblastoma (GBM)." (PMID 32226941, 2020). "Despite activated EGFR in glioblastomas, EGFR inhibitors have shown little benefit for glioblastoma patients." (PMID 32499560, 2020). "This modified HSV demonstrated selective infection and killing of EGFR-bearing glioblastoma tumor cells in vitro and improved viral penetration and survival in a glioblastoma multi-forme xenograft model." (PMID 33167307, 2020). "The amplification of EGFR was found to be more commonly present in primary glioblastomas (40%), and rarely present in secondary glioblastomas." (PMID 32290213, 2020). "Introduction of miRNA-7 to glioblastoma cells markedly decreased EGFR expression levels and synergistically enhanced the cytotoxicity of erlotinib." (PMID 32592373, 2020). "Inhibition of Kv1.1 by KAaH2 toxin targeting specifically Kv1.1 was shown to inhibit proliferation of glioblastoma via the Epidermal Growth Factor Receptor (EGFR) signaling pathway." (PMID 33381507, 2020). "While the majority of glioblastoma cells express either EGFR or EGFRvIII, a small fraction of tumor cells co-express EGFR and EGFRvIII." (PMID 31968687, 2020). "In fact, several agents (antibodies as well as small molecules) targeting EGFR in glioblastomas have already been tested in patients, but targeting EGFR has not provided therapeutic benefits." (PMID 32788653, 2020). "Here, we firstly showed that EGFR/MAPK hyperactivation results in epigenetic silencing of SIX3 through ZNF263 in glioblastoma." (PMID 32051553, 2020). "Epidermal growth factor receptor (EGFR) amplification and EGFR variant III (EGFRvIII, deletion of exons 2–7) are of clinical interest for glioblastoma." (PMID 32303258, 2020). "Studies have shown that the EGFR/PI3K/AKT/SREBP-1 signaling pathway can promote the progression of glioblastoma." (PMID 33604287, 2020). "EGFR is commonly amplified, overexpressed, or mutated in glioblastoma, so we evaluated the treatment efficacy of two EGFR inhibitors, erlotinib and gefitinib, and the glioblastoma standard-of-care alkylating agent temozolomide in our models." (PMID 32499560, 2020). "As a molecular signature of glioblastoma in that series, EGFR amplification is the most specific but least sensitive marker, with 99.8% specificity and 36.0% sensitivity." (PMID 30967140, 2019). "Downregulation of EGFR-MEK-ERK signaling pathway is sufficient to induce cellular senescence in glioblastoma cells." (PMID 30910997, 2019).